PRAMEF1 (PRAME family member 1)
Tractability: PROTAC: ubiquitination databases record sites on it.
Gene: Protein-coding gene on chromosome 1 (12,791,397 to 12,796,628, forward strand). Ensembl gene ENSG00000116721.
Gene Ontology:
Molecular function: ubiquitin-like ligase-substrate adaptor activity
Biological process: proteasome-mediated ubiquitin-dependent protein catabolic process; negative regulation of apoptotic process; negative regulation of cell differentiation; negative regulation of DNA-templated transcription; positive regulation of cell population proliferation
Cellular component: Cul2-RING ubiquitin ligase complex; cytoplasm
Genetic constraint (gnomAD): Loss-of-function variants: 21 observed, 36.17 expected, observed/expected ratio (o/e) 0.58, 90% interval 0.41 to 0.84. The upper end of that interval is the gene's LOEUF score, 0.84, which puts it in group 3 of 6, group 1 being the genes least tolerant of losing a copy. Missense variants: 497 observed, 510.23 expected, observed/expected ratio (o/e) 0.97, 90% interval 0.9 to 1.05. Synonymous variants: 200 observed, 204.73 expected, observed/expected ratio (o/e) 0.98, 90% interval 0.87 to 1.1.
Homologues: Orthologues: mouse Pramel12 (44% identical), rat Pramef8 (43% identical), mouse Pramel13 (41% identical), mouse Pramel21 (41% identical), mouse Pramel11 (41% identical), mouse Pramel24 (41% identical), mouse Pramel20 (41% identical), rat LOC120103107 (41% identical), mouse Pramel16 (40% identical), mouse Gm13040 (40% identical), mouse Gm13043 (40% identical), mouse Gm13057 (40% identical), and 78 more. Paralogues in human: PRAMEF14 (97% identical), PRAMEF13 (97% identical), PRAMEF2 (94% identical), PRAMEF18 (62% identical), PRAMEF19 (62% identical), PRAMEF10 (60% identical), PRAMEF17 (60% identical), PRAMEF33 (60% identical), PRAMEF12 (54% identical), PRAMEF7 (53% identical), PRAMEF8 (53% identical), PRAMEF20 (50% identical), and 12 more.